KIR2DL4 (killer cell immunoglobulin like receptor, two Ig domains and long cytoplasmic tail 4)
Description:
Receptor for non-classical major histocompatibility class Ib HLA-G molecules. Recognizes HLA-G in complex with B2M/beta-2 microglobulin and a nonamer self-peptide (peptide-bound HLA-G-B2M). In decidual NK cells, binds peptide-bound HLA-G-B2M complex and triggers NK cell senescence-associated secretory phenotype as a molecular switch to promote vascular remodeling and fetal growth in early pregnancy. May play a role in balancing tolerance and antiviral-immunity at maternal-fetal interface by keeping in check the effector functions of NK, CD8+ T cells and B cells. Upon interaction with peptide-bound HLA-G-B2M, initiates signaling from the endosomal compartment leading to downstream activation of PRKDC-XRCC5 and AKT1, and ultimately triggering NF-kappa-B-dependent pro-inflammatory response.
Synonyms: KIR-103AS; CD158d; KIR103AS; 103AS; 15.212; G9P; KIR-2DL4; KIR103
Tractability: Antibody: its Gene Ontology location is reachable by antibodies, with high confidence; UniProt places it where antibodies can reach, with medium confidence; UniProt predicts a signal peptide or a membrane-spanning region.
Gene: Protein-coding gene on chromosome 19 (54,803,610 to 54,814,517, forward strand). Ensembl gene ENSG00000189013.
Subcellular location: Cell membrane; Early endosome membrane
Pathways (Reactome):
Immune System: Immunoregulatory interactions between a Lymphoid and a non-Lymphoid cell
Gene Ontology:
Molecular function: MHC class Ib receptor activity; protein binding; transmembrane signaling receptor activity
Biological process: negative regulation of natural killer cell mediated cytotoxicity; positive regulation of cellular senescence; positive regulation of natural killer cell cytokine production; cellular defense response; immune response-inhibiting cell surface receptor signaling pathway; signal transduction
Cellular component: early endosome membrane; membrane; plasma membrane
Genetic constraint (gnomAD): Loss-of-function variants: 40 observed, 29.6 expected, observed/expected ratio (o/e) 1.35, 90% interval 1.05 to 1.75. The upper end of that interval is the gene's LOEUF score, 1.75, which puts it in group 6 of 6, group 1 being the genes least tolerant of losing a copy. Missense variants: 438 observed, 342.32 expected, observed/expected ratio (o/e) 1.28, 90% interval 1.18 to 1.38. Synonymous variants: 164 observed, 131.63 expected, observed/expected ratio (o/e) 1.25, 90% interval 1.1 to 1.42.
Homologues: Orthologues: chimpanzee KIR2DL4 (96% identical), mouse Kir3dl1 (32% identical), mouse Kir3dl2 (30% identical), rat Kir3dl1 (30% identical), tropical clawed frog xilr1 (15% identical). Paralogues in human: KIR3DL2 (69% identical), KIR3DL1 (67% identical), KIR3DL3 (62% identical), KIR2DL1 (47% identical), KIR2DL3 (46% identical), LILRB1 (35% identical), LILRB3 (34% identical), LILRB2 (33% identical), LILRB5 (31% identical), LILRA6 (30% identical), LILRB4 (28% identical), LILRA1 (27% identical), and 13 more.
Diseases named in the same sentence as KIR2DL4 in open-access papers:
KIR2DL4 is named in the same sentence as 38 diseases in open-access papers, as found by Europe PMC text mining. Sharing a sentence is not in itself a finding about the gene and the disease. The quoted sentences say what the papers report.
breast carcinoma (19 papers, 2017 to 2025). "We examined the association between HLA-G, its receptor KIR2DL4, mast cells, and breast cancer progression." (PMID 32023940, 2020). "Furthermore, in breast cancer, the interaction between HLA-G and the NK cell receptor KIR2DL4 amplifies the susceptibility of HER2-positive breast cancer cells to trastuzumab, elucidating the mechanisms underlying the resistance to trastuzumab." (PMID 38283362, 2023). "Engagement between HLA-G and killer-cell immunoglobulin-like receptor 2DL4 (KIR2DL4) desensitizes breast cancer cells to trastuzumab treatment or promotes metastasis by inducing matrix metalloproteinase (MMP)-9 expression." (PMID 41194925, 2025). "Our previous study had shown that blockade of KIR2DL4 interaction in NK cells can re-sensitize breast cancer to trastuzumab treatment, which indicated that KIR2DL4 was a pivotal immune checkpoint of NK cells." (PMID 40549069, 2025). "Our prior research demonstrated that inhibiting the interaction of KIR2DL4 in NK cells can enhance the efficacy of trastuzumab treatment in breast cancer, suggesting that KIR2DL4 plays a crucial role as an immune checkpoint in NK cells." (PMID 40549069, 2025). "In 2015, Ueshima and their colleagues found that the KIR2DL4 on human mast cells facilitates HLA-G-expressing breast cancer invasion and the subsequent metastasis." (PMID 40549069, 2025). "In breast cancer cells that exhibit high HLA-G expression, binding to KIR2DL4 on natural killer (NK) cells suppresses their anti-tumor activity, thereby reducing the therapeutic efficacy of trastuzumab." (PMID 39655080, 2024). "Experimental studies suggest that disrupting the HLA-G/KIR2DL4 pathway can enhance the immune response of NK cells against breast cancer cells, thereby improving trastuzumab’s anti-tumor effect." (PMID 39655080, 2024). "Trastuzumab responsiveness for HER2-positive breast cancer can be improved by blocking the HLA-G/KIR2DL4 signaling pathway." (PMID 37981615, 2024). "Studies revealed that KIR2DL4 activates the cytotoxicity of NK cells, and NK-92 cells stimulated with KIR2DL4 had higher cytotoxicity against breast cancer cells." (PMID 39387546, 2024). "KIR2DL4 can mediate a complicated cross‐talk between immune checkpoint and cytokines in breast cancer microenvironment and dictate distinct outcome of immunotherapy." (PMID 39159071, 2024). "We previously found that breast cancer cells express HLA-G, which inhibits the cytotoxicity of NK cells by binding to the receptor KIR2DL4." (PMID 37981615, 2024). "In our study, we found that HLA-G desensitizes breast cancer cells to trastuzumab by binding to the NK-cell receptor KIR2DL4 and the blockade of HLA-G/KIR2DL4 axis improves the vulnerability of HER2-positive breast cancer to trastuzumab treatment in vivo." (PMID 36960057, 2023). "Many studies have shown that HLA-G/KIR2DL4 expression in immune microenvironment were correlated with the prognosis and progression of breast cancer." (PMID 35185887, 2022). "In this review, we aim to summarize the roles of HLA-G/KIR2DL4 in breast cancer immune microenvironment." (PMID 35185887, 2022). "We also detected abundant KIR2DL4 expression on infiltrating NK cells in HER2 positive breast cancer tissues." (PMID 35185887, 2022). "In addition, it is also necessary to unravel the mechanisms underlying HLA-G/KIR2DL4 regulation of the immune microenvironment in breast cancer, hopefully providing a rationale for combined HLA-G and immune checkpoints targeting for the effective treatment of breast cancer." (PMID 35185887, 2022). "Our recent study found that KIR2DL4 synergizes with FcRγ to enhance NK cell activation and degranulation, while HLA-G binding to KIR2DL4 impairs the cytotoxicity of NK cells in HER2 positive breast cancer microenvironment." (PMID 35185887, 2022). "In breast cancer immune microenvironment, HLA-G can bind to its receptor, such as KIR2DL4, to induce immunosuppression." (PMID 35185887, 2022).
breast carcinoma (continued). "Our previous study had shown that HLA-G was a pivotal mediator of breast cancer resistance to trastuzumab, and blockade of the HLA-G/KIR2DL4 interaction can resensitize breast cancer to trastuzumab treatment." (PMID 35185887, 2022). "HLA-G can desensitize breast cancer cells to trastuzumab by binding to KIR2DL4, an atypical member of the KIR family, which responds to HLA-G via endosomal signaling." (PMID 36601109, 2022). "Then, we reviewed the expression of HLA-G/KIR2DL4 in breast cancer immune microenvironment and the potential of HLA-G/KIR2DL4 application in breast cancer immunotherapy." (PMID 35185887, 2022). "In this review, we aim to summarize and discuss the role of HLA-G/KIR2DL4 in the immune microenvironment of breast cancer." (PMID 35185887, 2022). "Recent studies have found that blocking the binding of KIR2DL4 to the ligand on NK cells can restore the sensitivity of breast cancer to trastuzumab." (PMID 35712981, 2022). "Our recent study has showed that HLA-G can desensitize breast cancer cells to trastuzumab by binding to the NK cell receptor KIR2DL4." (PMID 35185887, 2022). "Blocking HLA-G or KIR2DL4 also promoted trastuzumab-induced degranulation of NK cells cocultured with HER2-positive breast cancer cells." (PMID 34158475, 2021). "Blockade of HLA-G/KIR2DL4 signaling improved the vulnerability of HER2-positive breast cancer to trastuzumab treatment in vivo." (PMID 34158475, 2021). "Using clinical samples, we have shown that HLA-G-positive breast cancer cells interact directly with KIR2DL4-positive tissue mast cells immunohistochemically." (PMID 32023940, 2020). "To elucidate the importance of the interaction between KIR2DL4 on mast cells and HLA-G on cancer cells, we co-cultured the HLA-G-positive human breast cancer cell line MCF-7 cells with the human mast cell LAD2." (PMID 32023940, 2020). "Ozturk et.al found that the frame genes of KIR2DL4 were found in all breast cancer patients." (PMID 40549069, 2025). "Recent studies have found that KIR2DL4 might be a tumor suppressor via its activating potential in breast cancer, which is consistent with the results in our previous study." (PMID 40549069, 2025). "So far, the role of HLA-G/KIR2DL4 in breast cancer immunotherapy has been progressively elucidated." (PMID 35185887, 2022). "A deep understanding of the regulatory role of HLA-G/KIR2DL4 in the immune microenvironment of breast cancer might provide new ideas for the treatment of breast cancer." (PMID 35185887, 2022). "Based on its special structure, KIR2DL4 can mediate a complicated cross-talk between immune checkpoint and cytokines in breast cancer microenvironment, and dictate distinct outcome of immunotherapy depending on whether or not HLA-G is engaged." (PMID 35185887, 2022). "Our recent study reported that KIR2DL4, an alternative receptor of HLA-G, might be a novel target in breast cancer immunotherapy." (PMID 35185887, 2022). "In HER2-positive breast cancer, blocking HLA-G/KIR2DL4 signaling improved trastuzumab resistance." (PMID 36601109, 2022). "Finally, we probed the role of HLA-G/KIR2DL4 in the response of clinical breast cancer to trastuzumab using neoplastic specimens of trastuzumab-resistant and trastuzumab-sensitive patients." (PMID 34158475, 2021). "We next examined whether the trastuzumab-mediated interplay between HER2-overexpressing breast cancer cells and NK cells regulates HLA-G and KIR2DL4 expression." (PMID 34158475, 2021). "KIR2DL4 is reported to be related to vascular remodeling and breast cancer invasion." (PMID 28702027, 2017). "In a prior study, we discovered that HLA-G binds to the NK cell receptor KIR2DL4, desensitizing HER2-positive breast cancer cells to trastuzumab." (PMID 37981615, 2024). "HLA-G disrupts ADCC by binding to the NK cell receptor KIR2DL4, making HER2-positive breast cancer cells resistant to trastuzumab." (PMID 36210846, 2022).
breast carcinoma (continued). "Here, we established that the abundant expression of HLA-G on breast cancer cells and its engagement with the atypical KIR family receptor, KIR2DL4, on NK cells suppress ADCC and contribute to breast cancer resistance to trastuzumab." (PMID 34158475, 2021). "A recent study demonstrated that KIR2DL4 synergized with FcRγ to augment NK cell activation and degranulation, whereas the interaction of HLA-G with KIR2DL4 attenuated NK cell cytotoxicity in HER2-positive breast cancer." (PMID 38310272, 2024). "For example, interactions between NK cell receptor KIR2DL4 and HLA-G have recently been reported to be of importance in human breast cancer, and neither KIR2DL4 nor HLA-G were included in our panels." (PMID 37495775, 2023). "Here, we found that the nonclassical histocompatibility antigen HLA-G desensitizes breast cancer cells to trastuzumab by binding to the natural killer (NK) cell receptor KIR2DL4." (PMID 34158475, 2021). "Therefore, our study suggests novel approaches to improving trastuzumab efficacy in HER2-positive breast cancer patients, e.g., antibody- or CRISPR/Cas9-mediated depletion of HLA-G, or development of soluble KIR2DL4 or blockers for the HLA-G/KIR2DL4 interaction." (PMID 34158475, 2021). "Additionally, it has recently been demonstrated that human leukocyte antigen G (HLA-G) hinders ADCC by binding to the atypical KIR family receptor KIR2DL4 on NK cells, which may help explain why HER2-positive breast cancer is resistant to trastuzumab treatment." (PMID 36210846, 2022). "We observed that the HLA-G- or KIR2DL4-neutralizing antibody, but not the ILT2 antibody, significantly increased IFN-γ production by NK cells cocultured with breast cancer cells in the presence of trastuzumab." (PMID 34158475, 2021).
melanoma (7 papers, 2018 to 2025). A malignant, usually aggressive tumor composed of atypical, neoplastic melanocytes. "Elevated expression of KIR2DL4 has been observed in certain tumor types, including melanoma, lung cancer, and ovarian cancer, indicating its role in tumor evasion." (PMID 40549069, 2025). "In this study, six genes (ADCYAP1R1, GPI, IFITM1, KIR2DL4, LIF, and NTS) were identified as being closely associated with prognosis among a pool of 1793 melanoma-related genes." (PMID 38217549, 2024). "Six genes closely associated with the prognosis of melanoma patients, including ADCYAP1R1, GPI, IFITM1, KIR2DL4, LIF and NTS, were elected to fabricate a prognosis model." (PMID 38217549, 2024). "The IHC staining results showed that Ube2L6, SRPX2, and IFIT2 were expressed at higher levels, while CLEC4E, END3, and KIR2DL4 were expressed at lower levels in 25 melanoma specimens." (PMID 34660598, 2021). "According to immunohistochemistry staining results, Ube2L6, SRPX2, and IFIT2 were expressed at higher levels, while CLEC4E, END3, and KIR2DL4 were expressed at lower levels in 25 melanoma specimens." (PMID 34660598, 2021). "Multiple studies have demonstrated that the expression levels of KIR2DL4 may serve as a potential prognostic marker for melanoma, indicating the likelihood of disease aggressiveness." (PMID 40549069, 2025). "Furthermore, KIR2DL4 was found to be highly expressed in melanoma and contribute to the immunotherapy effect and prognosis in patients with melanoma via activating the immune cells such as NK cells and T cells." (PMID 40864319, 2025). "Our findings indicate that ADCYAP1R1, GPI, and NTS may contribute to a poor prognosis in melanoma patients, while IFITM1, KIR2DL4, and LIF are more likely to be associated with a better prognosis in individuals with melanoma." (PMID 38217549, 2024). "In this study, six genes (ADCYAP1R1, GPI, IFITM1, KIR2DL4, LIF, and NTS) that exhibited strong correlation with the prognosis of melanoma patients were identified." (PMID 38217549, 2024). "We focused on the potential prognostic value of EDN3, CLEC4E, SRPX2, KIR2DL4, UBE2L6, and IFIT2 as immune scores for melanoma patients." (PMID 34660598, 2021). "Obviously, ADCYAP1R1, GPI and NTS might lead to poor prognosis for melanoma patients, while IFITM1, KIR2DL4 and LIF are more likely to improve outcomes." (PMID 38217549, 2024).
endometriosis (6 papers, 2018 to 2023). The growth of functional endometrial tissue in anatomic sites outside the uterine body. "The analysis of polymorphisms of HLAG gene coding for a ligand for KIR2DL4 and LILRB2 receptors has revealed that endometriosis in Polish women is associated with a lower frequency of its −964GG genotype (−964A > G; rs1632947)." (PMID 31540116, 2019). "KIR2DL4 and KIR3DL1 are members of the killer cell immunoglobulin-like receptor family and might be associated with the pathogenesis of endometriosis through their involvement in the regulation of NK cell activity." (PMID 37662927, 2023). "The study of Polish scientists analyzed whether polymorphisms of HLA-G, KIR2DL4, LILRB1 and LILRB2 genes may affect susceptibility to endometriosis and disease progression." (PMID 34638893, 2021). "In this study we investigated whether HLA-G, KIR2DL4, LILRB1 and LILRB2 polymorphisms may influence susceptibility to endometriosis and disease progression." (PMID 29234882, 2018). "Therefore, the aim of this retrospective study was to evaluate the association of the SNPs in genes coding for KIR2DL4, LILRB1 and LILRB2 receptors and their ligand HLA-G with susceptibility to and severity of endometriosis as potential non-invasive markers for the diagnosis of this disease." (PMID 29234882, 2018). "It should be stressed, however, that the functional role of HLA-G in the context of KIR2DL4 and LILRB1 receptors in course of endometriosis remains unknown and requires further investigations." (PMID 31540116, 2019).
lupus (5 papers, 2012 to 2024). "Swalhaet al. reported that combining the total genetic risk with the demethylation status of two T cell related loci linked to lupus, KIR2DL4, and PRF1, men may need much more DNA demethylation to achieve similar lupus flares than women." (PMID 34769338, 2021). "In systemic lupus erythematosus (SLE), the overexpression of CD11a, CD40L, CD70, KIR2DL4, and PRF1 in T lymphocytes is associated with DNA hypomethylation in promoter regions." (PMID 38473997, 2024). "Previous studies have suggested that HOXB3, GH1 and KIR2DL4 are involved in autoimmune disease such as Thyroid-associated orbitopathy (TAO), Type 1 diabetes (T1DM), and Systemic lupus erythematosus (SLE)." (PMID 33384687, 2020). "Subsequently, hypomethylation of certain genes have been identified as important in lupus T cells, such as ITGAL (CD11a), CD40LG (CD40L), TNFSF7 (CD70), Killer-cell immunoglobulin-like receptor (KIR2DL4), perforin (PRF1), and CD5 in lupus B cells." (PMID 25566322, 2014). "Less methylation of the KIR2DL4 promoter, for example, has been detected in SLE patients Although KIRs are preferentially expressed on NK cells, T cells from lupus patients have higher levels of KIR genes and their expression seems to be proportional to disease activity." (PMID 23029299, 2012).
preeclampsia (4 papers, 2014 to 2025). Preeclampsia is a hypertensive disorder of pregnancy that is characterized by new-onset hypertension with proteinuria presenting after 20 weeks of gestation, and depending on mild or severe forms may initially present with severe headache, visual disturbances, and hyperreflexia. "On the other hand, although we observed significant associations between certain maternal KIR2DL4 and fetal HLA-G polymorphisms and preeclampsia, these findings need to be validated in larger and more diverse populations." (PMID 39144721, 2024). "Despite the lack of a direct association between maternal KIR gene polymorphisms and preeclampsia, specific maternal KIR2DL4 and fetal HLA-G combinations warrant further exploration." (PMID 39144721, 2024). "Therefore, this study suggested that the combination of maternal KIR2DL4 and fetal HLA-G polymorphisms was associated with preeclampsia in a Han Chinese population." (PMID 39144721, 2024). "However, the presence of a fetal G*01:06 allele in combination with the maternal KIR2DL4*006 allele has been reported to be significantly associated with preeclampsia risk in multigravida pregnancies, suggesting a gene–gene interaction." (PMID 25566263, 2014). "Maternal allele frequencies for all SNP loci of the KIR2DL4 gene and HLA-G gene were not significantly different between the preeclampsia group and the control group." (PMID 39144721, 2024). "Therefore, we concluded that the maternal KIR2DL4 gene is not strongly associated with the development of preeclampsia if it is studied as an independent genetic factor." (PMID 39144721, 2024).